INS (insulin)
Diseases named in the same sentence as INS in open-access papers (continued):
Sharing a sentence is not in itself a finding about the gene and the disease.
diabetes (continued). "Reduced production of insulin and insulin resistance are the main causes of diabetes." (PMID 38255262, 2024). "This signifies the importance of addressing the risk of diabetes in the obese population since it is crucial for prevention as it helps improve insulin sensitivity, enhance metabolic and cardiovascular health, promote healthy aging, reduce healthcare costs, and improve quality of life." (PMID 39104999, 2024). "Obesity induces insulin resistance and impairs insulin signaling, causing diabetes." (PMID 39033139, 2024). "Furthermore, pancreatic inflammation leads to the decrease of islet cell mass leading to the loss of glucagon, insulin, and pancreatic polypeptide, which difficult the control of diabetes with large variations in blood glucose." (PMID 39030443, 2024). "This condition encompasses two primary types: type 1 diabetes mellitus (T1DM), characterized by deficient insulin production due to autoimmune destruction of pancreatic cells, and type 2 diabetes mellitus (T2DM), which involves insulin resistance and insufficient insulin production." (PMID 39435211, 2024). "ICPis-associated diabetes may be noted in young patients with rare tumours, and regular insulin level monitoring after use is necessary." (PMID 38872175, 2024). "Abdominal fat improves the risk of diabetes by inhibiting insulin production by β cells." (PMID 40777932, 2024). "Like human diabetes, high-carbohydrate diets may play a role in predisposing cats to obesity and diabetes due to increased blood glucose and insulin levels." (PMID 39591292, 2024). "As a conclusion, rosehip extract's beneficial effects in diabetes management are linked to its ability to modulate cell signaling pathways involved in glucose metabolism and insulin sensitivity, ultimately influencing the overall metabolic state and reducing the risk of diabetes progression." (PMID 38765085, 2024). "This study concluded that insulin injection improved the expression level of the GFAP and NSE genes, but it can be said that insulin injection had different relative effects on gene expression in the brain nuclei due to the degree of disruption caused by diabetes." (PMID 38639646, 2024). "Additionally, zinc is crucial in the biochemistry of insulin and glucagon within pancreatic β- and α-cells, playing a key role in the synthesis, storage, and release of insulin, and is linked to diabetes and metabolic syndrome." (PMID 39872136, 2024). "Supervised controlled feeding trials to test the metabolic effects of eTRF independent of body weight changes have shown large improvements in insulin sensitivity and beta cell responsiveness and reduced 24 h glucose levels in overweight individuals at risk of diabetes." (PMID 37971503, 2024). "Obesity is regarded to constitute an important risk factor for developing diabetes, especially type 2 diabetes, which is considered to be the most frequent form of this disease, characterized by resistance to insulin, so the term “diabesity” has also been used to include both syndromes." (PMID 38255850, 2024). "Women enrolled in the Tianjin Gestational Diabetes Mellitus Prevention Program, had significant weight loss and reduction in plasma insulin levels in the lifestyle intervention arm compared to the control group during the first year but it is unclear if these effects were sustained." (PMID 39221169, 2024). "Diabetes is caused by the absolute or relative insufficient production of insulin." (PMID 38731945, 2024). "The hypothesis that vitamin D supplementation can reduce diabetes risk is biologically plausible because vitamin D regulates insulin secretion from the pancreas by enhancing β-cell function and inhibits insulin resistance by mitigating chronic inflammation." (PMID 39339785, 2024). "One of the main causes of decreased insulin secretion capacity in diabetes is oxidative stress." (PMID 39396974, 2024).
diabetes (continued). "However, after adjustment for M (model 3) and further adjustment for AIR and SWIA heritage (model 4) the association between insulin AUC/iAUCs with risk of diabetes was attenuated (p-values > 0.05)." (PMID 38987291, 2024). "While the role of dairy fat remains unclear, the collective effects of dairy's nutritional profile appear to act through pathways improving glycemic control and insulin sensitivity to reduce diabetes risk." (PMID 38800249, 2024). "However patients with insulin-deficient diabetes require additional insulin therapy, promoting imitation of hormonal interaction during postprandial state." (PMID 38579770, 2024). "Furthermore, a balanced eating plan, regular physical activity, and collaboration with healthcare professionals for insulin therapy adjustments can mitigate the risk of diabetes-related complications." (PMID 38882982, 2024). "Substantial oxidative stress has been observed in the brains of older people under 90 years of age with diabetes and elevated insulin levels, which may underlie the link between diabetes and dementia." (PMID 38542318, 2024). "Consistent with this, although Insr knockout (KO) causes only mild diabetic symptoms with impaired insulin secretory function and total IR in β cells, Insr/Igf1r double KO causes overt diabetes associated with reduced β cell mass, increased apoptosis and severely compromised β cell function." (PMID 38418586, 2024). "Therefore, both systemic arterial hypertension and diabetes mellitus (especially if treated with insulin therapy) appear to be risk factors for SACS." (PMID 38392602, 2024). "Through its interaction with thyroid activity, iodine at elevated levels may lead to insufficient insulin production, which in turn can cause insulin resistance and/or diabetes, both of which have an adverse effect on fertility." (PMID 39683543, 2024). "This study explores whether non-insulin diabetes medications can lower this risk compared to insulin." (PMID 39001440, 2024). "Multiple known and unknown mechanisms are involved in β-cell dysfunction associated with impaired insulin secretion and diabetes mellitus." (PMID 38966213, 2024). "Insulin instilled as eye drops has been shown to readily reach the retina without causing hypoglycemia, and clinical studies of insulin eye drops in healthy volunteers or patients with diabetes showed that this approach is well tolerated." (PMID 39110798, 2024). "If Lgr4 loss in humans similarly induces insulin resistance, it could exacerbate the risk of developing diabetes, particularly type-2 diabetes, which is characterized by insulin resistance and impaired insulin secretion." (PMID 39033139, 2024). "Further studies might be needed to confirm the association of the TyG index with lipid-lowering agents and insulin therapy in CAD patients with diabetes." (PMID 38184572, 2024). "High temperatures affect insulin sensitivity and cause an increased incidence of diabetes mellitus." (PMID 38545021, 2024). "Previous studies indicated thyroid dysfunction and diabetes mellitus are closely linked since thyroid hormones modulated by hypothalamic-pituitary-thyroid axis has an impact on glucose homeostasis and insulin sensitivity can influence the feedback of thyroid hormones in turn." (PMID 39678197, 2024). "We sought to investigate if β-cells closer to α-cells, interact more with immune cells during T1D, as the destruction of these cells could explain the loss in the first phase of insulin response observed in individuals with pre-diabetes." (PMID 38979061, 2024). "Similarly, among the Greek Cypriots, the HHEX rs5015480 has been linked to altered insulin secretion, cellular function, and diabetes susceptibility." (PMID 39659616, 2024). "Interestingly, other diabetes medications, such as insulin and sulfonylurea derivatives, were associated with a decreased risk of AMD." (PMID 38996175, 2024).
diabetes (continued). "This may have impacted the breadth of insights collected and constrained the exploration of challenges unique to specific types of diabetes, particularly those associated with type 1 diabetes and insulin therapy management." (PMID 39845677, 2024). "Diabetes is a metabolic disease characterized by chronic hyperglycemia caused by diminished insulin sensitivity in peripheral tissues as well as relatively insufficient insulin action due to impaired insulin secretion from pancreatic β cells." (PMID 38839813, 2024). "In case of insufficient compliance with those recommendations, the addition of insulin-sensitizing substances (drugs and/or food supplements) should be applied in the identified subjects in order to counteract the risk of diabetes, cardiovascular diseases, neoplasms, and neurodegenerative diseases." (PMID 39457728, 2024). "It was previously shown that HK2 expression is insulin-responsive, and in diabetes mellitus, HK2-associated unscheduled glycolysis may be a key initiator of insulin resistance and the development of vascular complications." (PMID 39044840, 2024). "The increased risk of developing tumors in diabetes mellitus might be due to an upregulation of the proliferative pathway of insulin signaling in the setting of hyperglycemia and insulin resistance." (PMID 39518998, 2024). "Additionally, some studies show that patients with diabetes treated with insulin have an increased risk of fracture." (PMID 38541119, 2024). "Physiological studies have confirmed that IPV causes diabetes by exacerbating stress and depression; the stress caused by IPV in women affects the hypothalamus-pituitary-adrenal axis, thereby increasing cortisol secretion and resistance of cells to insulin and causing diabetes." (PMID 39639251, 2024). "The association between iodine deficiency and diabetes may be mediated through insulin, given that research has identified a correlation between iodine deficiency and insulin resistance." (PMID 39212589, 2024). "Akkermansia muciniphila, has been associated with protection against diabetes and obesity in animal studies, may improve insulin sensitivity and reduce inflammation, further enhancing intestinal epithelial integrity in humans." (PMID 38633602, 2024). "As such, the VAI could be useful for measuring adipose tissue allocation and features, which are related to increased diabetes risk and have an inverse relationship with insulin sensitivity." (PMID 39698032, 2024). "Exercise, however, may raise the risk of hypoglycemia in diabetes individuals using insulin or insulin secretagogues, according to previous research." (PMID 38306364, 2024). "However, it is important to note that low-dose insulin cannot fully reverse the damage caused by diabetes." (PMID 38774757, 2024). "Intriguingly, the pancreatitis group may be often associated with positive diabetes-specific antibodies as well as preserved insulin release, since, in this group, elevated lipase was commonly reported." (PMID 39518461, 2024). "Diabetes caused by this pathogenic variant may be effectively treated with oral antidiabetic agents that lower the need for endogenous insulin secretion (ie, metformin and SGLT2 inhibitor)." (PMID 39027635, 2024). "Furthermore, we investigated a pilot cohort with evidence of insulin secretion disorder and screened for rare, pathogenic mutations of insulin secretion (monogenetic forms of diabetes, MODY)." (PMID 38550917, 2024). "These diseases mainly included metabolic diseases and neurological diseases, among which diseases directly associated with diabetes were Diabetes Mellitus, Experimental (C0011853), Diabetes Mellitus, Non-Insulin-Dependent (C0011860), and Insulin Resistance (C0021655)." (PMID 38338442, 2024). "Based on the described findings, it is expected that in certain patient subgroups, earlier initiation of insulin treatment may be crucial to improving control and preventing acute and chronic complications associated with diabetes." (PMID 38559691, 2024).
diabetes (continued). "Diabetes mellitus (DM) is a disease state caused by the pancreas’ inability to produce insulin, as in type I DM, or the body’s inability to utilize the insulin produced, a so-called insulin sensitivity, as is the case in type II DM (T2DM)." (PMID 38586157, 2024). "One of these diseases is diabetes mellitus (DM), a progressive metabolic condition characterized by chronic hyperglycemia caused by an inadequate pancreatic β-cell secretion, an impaired action of insulin, or both, in different proportions." (PMID 39000165, 2024). "Hyperglycemia in diabetes could lead to glucose toxicity and eventually cause oxidative stress through the generation of free radicals in the body that are detrimental to insulin-secreting β-cells in the pancreas." (PMID 38786486, 2024). "Butyrate is known to affect insulin sensitivity, therefore, increased butyrate synthesis caused by an enhancement of the butyrate-producing intestinal bacteria is considered as one of the methods to prevent or treat diabetes." (PMID 39839113, 2024). "Indeed, diabetes is characterized by high blood glucose levels that result from insulin deficiency, in the context of β- cell dysfunction, insulin resistance or both." (PMID 39415790, 2024). "The association between insulin therapy and the development of other diabetes complications may necessitate further trials." (PMID 39295783, 2024). "Diabetes mellitus refers to a group of chronic endocrine metabolic disorders that are characterised by a loss of glycaemic control, leading to elevated blood glucose concentration due to either insulin resistance or inadequate insulin production." (PMID 38651404, 2024). "Similarly, we also found a significant synonymous variant in the RNR2 gene (MT:2000C>T), which encodes Humanin, a peptide shown to improve insulin sensitivity in animal models of diabetes mellitus." (PMID 39659613, 2024). "For instance, T. foenum-graecum improves insulin sensitivity and secretion, while R. officinalis exhibits strong antioxidant properties that may help mitigate oxidative stress associated with diabetes." (PMID 39452489, 2024). "Thus, studies of insulin-deficient diabetes are often performed with levels of hyperglycemia over those found in even poorly controlled human diabetes." (PMID 37880477, 2024). "The impact of physical activity on reducing the risk of developing undiagnosed diabetes is clear because, during physical activity, glucose uptake into active muscles increases by increasing insulin sensitivity and allowing muscle cells to use glucose efficiently." (PMID 38713690, 2024). "The use of certain emulsifiers—additives used to improve products’ texture, appearance, and mouthfeel—has been associated with intestinal inflammation, with deleterious effects on gut microbiota and permeability, as well as insulin resistance and the potential increased risk of diabetes." (PMID 38816268, 2024). "Taken together, these results support the hypothesis that diabetes-associated metabolic changes (impaired glucose control and insulin resistance) likely favor neurodegeneration and cerebral pathology to a lower extent." (PMID 38190014, 2024). "The postprandial glucose findings in this study showed a tendency towards a lower response in the UN group without BC treatment and are consistent with studies that relate early nutritional deficiency with metabolic adult problems like T2 diabetes and obesity due to a reduction in insulin secretion." (PMID 38999749, 2024). "Dairy products contain various nutrients and bioactive components that may improve insulin sensitivity and secretion through several interconnected mechanisms to lower diabetes risk." (PMID 38800249, 2024). "Our study suggests that central insulin injection could improve pain sensation and cell damage caused by diabetes." (PMID 38639646, 2024).
diabetes (continued). "Diabetes is a multifactorial disease characterized by impaired metabolism of carbohydrates, lipids, and proteins and is caused by insulin resistance, impaired insulin secretion, or a combination of both." (PMID 38778308, 2024). "Includes therapy, dental implants, alveolar bone loss, diagnosis, radiography, apical periodontitis, surgery, management Group 4 contains 26 keywords (in yellow) and includes risk, diabetes, metabolic syndrome, blood pressure, insulin-resistance, c-reactive protein, markers, glycemic control." (PMID 38800469, 2024). "HAP1, a class of proteins tightly associated with Htt, may also contribute to the disruption of insulin vesicle transport and insulin secretion in HD-associated diabetes." (PMID 38975245, 2024). "Diabetes support group and associations provide patient support, counselling, advocacy and sometimes free or affordable consumables and medications such as glucose monitoring devices and insulin." (PMID 38768080, 2024). "The worsening of renal conditions is a clear indication of inflammation, as stated for patients suffering from pathological obesity, that are characterized by impaired insulin sensitivity and higher levels of HbA1c too, a diagnostic marker of pre-diabetes and T2D diabetes." (PMID 38904913, 2024). "Experimental and observational data indicate that vitamin D signaling is involved in insulin secretion and sensitivity, suggesting that vitamin D deficiency could potentially aggravate diabetes risk." (PMID 38525711, 2024). "We have previously identified phospholipid metabolites, including choline, glycerophosphoethanolamine, and GPC, as potential novel biomarkers of obesity-associated insulin sensitivity when compared with obese insulin resistant and type 2 diabetes mellitus (T2D) individuals." (PMID 39195553, 2024). "However, in the AKI group, there were more patients with diabetes and insulin use, which increased the risk twofold, an expected and widely identified result." (PMID 38285316, 2024). "While SGLT-2 inhibitors alone do not cause significant hypoglycemia, this risk can be increased in patients on concurrent insulin and sulfonylureas, and it may be beneficial for patients’ primary diabetes mellitus management team to be involved in these cases." (PMID 39093374, 2024). "According to the American Diabetes Association (ADA), type 1 diabetes mellitus is defined as an autoimmune β-cell destruction, which leads to absolute insulin deficiency, while type 2 diabetes mellitus is defined as a progressive loss of β-cell insulin secretion mainly related to insulin resistance." (PMID 38667504, 2024). "More in detail, previous research has indicated that, in particular, systemic therapy is linked to diabetes by interfering with insulin secretion (e.g., immune checkpoint inhibitors), reducing insulin sensitivity (e.g., mTOR inhibitors), or both (e.g., selective estrogen receptor modulators)." (PMID 39445809, 2024). "Although reprogramming cells to induce insulin secretion is an attractive possibility for diabetes therapy, the molecular mechanisms underlying the process of transdifferentiation of endocrine cells of the pancreatic islets into β-cells in humans have not been fully elucidated." (PMID 39045459, 2024). "In diabetes management, cilostazol may enhance the peripheral circulation and insulin sensitivity, potentially augmenting the hypoglycemic effects of drugs like insulin or sulfonylureas, thereby increasing the risk of hypoglycemia." (PMID 39846696, 2024). "Furthermore, the study revealed that 32% of patients with diabetes using MDI were at risk of miscalculating their insulin dose." (PMID 39411309, 2024). "The American Diabetes Association (ADA) describes DM as a collection of metabolic disorders marked by increased blood sugar levels because of deficiencies in the production of insulin, its action, or both." (PMID 38784356, 2024).